MKX-AS1 (MKX antisense RNA 1)
Gene: Long non-coding RNA gene on chromosome 10 (27,744,786 to 27,767,794, forward strand). Ensembl gene ENSG00000230500.
Diseases named in the same sentence as MKX-AS1 in open-access papers:
MKX-AS1 is named in the same sentence as 1 disease in open-access papers, as found by Europe PMC text mining. Sharing a sentence is not in itself a finding about the gene and the disease. The quoted sentences say what the papers report.
esophageal cancer (1 paper, 2023). A primary or metastatic malignant neoplasm involving the esophagus. "Therefore, assessing MKX/MKXAS1 expression, MMR status, and MSI can be crucial in determining prognosis and guiding treatment decisions for gastric, pancreatic, and esophageal cancers." (PMID 37242540, 2023).